SSRP1 (structure specific recognition protein 1)
Diseases named in the same sentence as SSRP1 in open-access papers (continued):
Sharing a sentence is not in itself a finding about the gene and the disease.
tumor (31 papers, 2011 to 2026). "In vitro treatment of tumor cells with CBL0137 resulted in FACT binding to chromatin as evidenced by SSRP1 loss from the soluble fraction and accumulation within the chromatin pellet in treated samples." (PMID 39518148, 2024). "Similar result was also obtained in the long‐term colony formation experiments, suggesting that the association of SSRP1 with pyruvate is required for tumor cell survival upon DNA damage." (PMID 35048565, 2022). "The results showed that the expression of rSSRP1 R54A dramatically attenuated pyruvate‐enhanced tumor cell viability after etoposide treatment, which confirms that the association of pyruvate with SSRP1 is also required for pyruvate supplementation‐enhanced tumor cell survival upon DNA damage." (PMID 35048565, 2022). "Existing studies have shown that SSRP1 overexpression is found in various tumour cells compared with normal cells." (PMID 40468947, 2025). "The analysis of GSE160119 and Group1 (scRNA‐seq) revealed that SSRP1 mRNA expression was significantly higher in PTCL tumor cells and increased during progression." (PMID 40344476, 2025). "For example, the facilitates chromatin transcription complex (FACT), which consists of the histone chaperones SUPT16H and SSRP1, has been proven to be remarkably upregulated and contribute to tumor progression by promoting oxidative stress adaptation in HCC10." (PMID 38561384, 2024). "Since SSRP1 is involved in platinum compound‐induced DNA repair and promotes chemotherapy resistance, we assessed if lncSLCO1C1 regulates tumour response to oxaliplatin chemotherapy." (PMID 35474446, 2022). "Taken together, we concluded that lncSLCO1C1 mediate tumour resistance to chemotherapy with oxaliplatin by enhancing SSRP1‐induced DNA repair in GC cells, resulting in poor patient overall survival." (PMID 35474446, 2022). "Analysis of DEPDC1 expressions in human tumour tissues from the UALCAN database indicated that SSRP1 is upregulated in several tumour tissues." (PMID 36072787, 2022). "We next evaluated the in vitro effects of CBL0137, a drug that traps SSRP1 into chromatin, on the growth of HGSC cell lines and HGSC patient-derived tumor cells expressing varying levels of SSRP1." (PMID 36539830, 2022). "More importantly, compared to that of rSSRP1 WT, rescued expression of rSSRP1 R54A only slightly recovered the viability of SSRP1‐depleted tumor cells after etoposide treatment." (PMID 35048565, 2022). "SSRP1 is identified to bind specifically to the double strand of DNA in combination with anti-tumor agents to execute cell death by blocking replication." (PMID 35831348, 2022). "To investigate the role of pyruvate–SSRP1 interaction in tumor cell survival, we depleted SSRP1 in U251 or U87 cells and rescued these cells with rSSRP1 WT or R54A." (PMID 35048565, 2022). "Although previous studies on SSRP1 have focused on chromatin-related aspects, this study will explore the potential function of the SSRP1 expression in tumor immunology." (PMID 33688504, 2021). "In vivo the SSRP1 subunit enhanced xenograft tumor growth/proliferation and SSRP1 overexpression in vitro promoted EMT." (PMID 32477926, 2020). "Curaxins, compounds with activity against SSRP1, have been shown to induce apoptosis in tumor cells." (PMID 31839745, 2019). "CBL0137 treatment by ILP reduces SSRP1 expression, suppresses HSF1/hsp70 transcription, and causes tumor cell death, and its efficacy can be improved by hyperthermia." (PMID 30581774, 2018). "First, previous tumor analysis used only SSRP1 staining, while in the current study, an optimized SPT16 staining procedure was employed to get data for the expression of both FACT subunits." (PMID 25402820, 2014). "However, the current research on SSRP1 mainly focuses on the field of tumour, and the research on SSRP1 in other normal tissues is rarely reported." (PMID 40468947, 2025).
tumor (continued). "Similarly, The IC50 values of CBL0137 were 0.3–1.3 μM in SSRP1-high patient-derived tumor cells compared to > 3.8 μM in SSRP1-low patient-derived tumor cells." (PMID 36539830, 2022). "The pyruvate produced by PKM2 directly binds to SSRP1, which increases the association of FACT complex with γH2AX and subsequently facilitates FACT‐mediated chromatin loading of γH2AX, ultimately promoting DNA repair and tumor cell survival." (PMID 35048565, 2022). "Consequently SSRP1-low expressing HGSCs cell lines or tumor cells or SSRP1-inhibition in SSRP1-high HGSCs lines significantly reduced sensitivity to CBL0137." (PMID 36539830, 2022). "In addition, we investigated the correlation between SSRP1 and tumor-infiltrating immune cells in different tumor microenvironments by TIMER, online hepatocellular single cell sequencing, and other databases." (PMID 33688504, 2021). "Interestingly, the SSRP1 expression was higher in both tumor Treg and exhausted CD8+ T cells than in adjacent tissues." (PMID 33688504, 2021). "Among them, SSRP1 and SEPT2 that participate in cell cycle progression or MYCBP, HMGA1 and MT2A involved in cell growth and proliferation and previously linked to tumor progression." (PMID 24870930, 2014). "Some discrepancies were observed on the RNA level, which may explain the results of study showing that inactivation SSRP1 or SPT16 in tumor cells affected expression of slightly different sets of genes." (PMID 21998152, 2011). "LncSLCO1C1 promotes tumour progression and resistance to oxaliplatin therapy by enhancing cell growth and preventing DNA damage through interacting and scaffolding the SSRP1/H2A/H2B complex in nucleus and absorbing both miR‐211‐5p and miR‐204‐5p in cytoplasm to increase the expression of SSRP1." (PMID 35474446, 2022). "To further explore the detail mechanism by which lncSLCO1C1 mediates the function of oxaliplatin in increasing SSRP1 expression, we pulled down miRNAs from tumour cells by lncSLCO1C1 and obtained thousands of miRNAs that might interact with lncSLCO1C1 in GC cells." (PMID 35474446, 2022). "SSRP1 depletion markedly decreased the viability of tumor cells after etoposide treatment, while rescued expression of rSSRP1 WT completely recovered the viability of tumor cells to that of shNT‐expressing cells, excluding the off‐targeting possibility of shSSRP1." (PMID 35048565, 2022). "To determine whether pyruvate supplementation promotes tumor cell survival upon DNA damage through its binding to SSRP1, we supplemented SSRP1‐depleted U251 or U87 cells rescued with rSSRP1 WT or pyruvate‐binding deficient mutant R54A with or without pyruvate, followed by the treatment of etoposide." (PMID 35048565, 2022). "Indeed, lncSLCO1C1 mediates tumour resistance to oxaliplatin as downregulation of lncSLCO1C1 re‐sensitised the platinum‐resistant tumour to fully response oxaliplatin treatment by reducing the interaction of SSRP1 with H2A/H2B and increasing the expression of γH2AX in tumour cells." (PMID 35474446, 2022). "Specifically, PIWIL4, SATB1, GSE1, NCOR1, SAP30L, ATM, and BMI1 were significantly downregulated in tumor tissues relative to normal controls, while BUB1, CHEK1, MASTL, DNAJC2, UBE2D1, and SSRP1 showed pronounced upregulation." (PMID 41208974, 2025). "Meanwhile, increasing research on chemical compounds such as SSRP1, which can reduce the proliferation of NPC tumor cells, provides new options for more effective treatment." (PMID 36963168, 2023). "SSRP1 can regulate the proliferation and metastasis of HCC, its aberrant overexpression is related to higher serum AFP level, larger tumor size, and higher T stage of HCC patients." (PMID 35646665, 2022). "We show that SSRP1 inhibition using a small molecule, CBL0137, that traps SSRP1 onto chromatin, exerts a significant anti-growth activity in vitro against HGSC cell lines and patient-derived tumor cells, and also reduces tumor burden in vivo." (PMID 36539830, 2022).
tumor (continued). "CBL0137 induced DNA repair deficiency via inhibition of the HR repair pathway and sensitized SSRP1-high HR-proficient HGSC cell lines and patient-derived tumor cells/xenografts to the PARPi, Olaparib in vitro and in vivo." (PMID 36539830, 2022). "We next evaluated the synergistic anti-tumor activity of CBL0137 and Olaparib in vivo using the HR-proficient SSRP1-high DF149 HGSC PDX." (PMID 36539830, 2022). "We found that CBL0137, an SSRP1 inhibitor, inhibits the growth of HGSC cell lines and patient-derived tumor cells in vitro and in vivo." (PMID 36539830, 2022). "This study elucidates the important role of SSRP1 in HCC and provides potential relationships and mechanisms for the interaction of SSRP1 with tumor immunity." (PMID 33688504, 2021). "Thus, we asked whether miR-4784 functioned as a tumor suppressor by targeting SSRP1 in HCC cells." (PMID 32970959, 2020). "Upon receipt of a sample, part of the tumor was taken for IHC analysis of SSRP1 and SPT16 subunits and the remaining tumor was implanted into donor SCID mice." (PMID 25402820, 2014). "Mechanistically, CBL0137 significantly reduced mitotic activity and induced tumor cell death by targeting the EWSR1-FLI1-FACT pathway and disrupting the transcription of EWSR1-FLI1, SSRP1 (structure-specific recognition protein 1), and their downstream effectors." (PMID 40584293, 2025). "Also, three of seven patient-derived tumor lines including DF86, DF149, and DF181, expressed high levels of SSRP1 compared to the other four patient-derived tumor lines." (PMID 36539830, 2022). "Since SSRP1 expression is high in HGSCs, in this study we evaluated the anti-cancer activity of CBL0137 in a range of pre-clinical models of HGSC including cell lines, patient-derived tumor cells ex vivo, syngeneic murine models and PDXs." (PMID 36539830, 2022). "SSRP1 expression was closely interrelated to the TNM stage, lymph node metastasis and tumour size." (PMID 35291495, 2022). "The effects of CBL0137 on these pathways, culminating in tumor cell death, are mediated by the inhibition of FACT, a chromatin remodeling complex composed of SSRP1 and SPT16 subunits, that is involved in the transcription of genes with highly ordered chromatin structure, replication, and mitosis." (PMID 25402820, 2014). "Normal and tumour tissues from such patients were analysed by qRT-PCR for the following 12 genes; six from RNA-seq: CLDN1, MAGEB2, CD24, CEACAM6, IL1B and ISG15 and six from RNA-seq and proteomics cross-linking: AKR1C3, TNFAIP2, RAB7A, LGALS3BP, PSCA and SSRP1." (PMID 36428603, 2022). "As anticipated, the normal liver did not have any detectable SSRP-1, consistent with the observation of FACT overexpression in tumor cells." (PMID 39518148, 2024). "Expression of the SSRP1 and SPT16 subunits of FACT was studied by immunohistochemistry in normal tissues of adult mice (FVB, 8-12 weeks old, male and female) and humans (control non-cancerous tissues from cancer patient on tumor tissue microarrays (TMA) provided by RPCI Pathology Network Recourse)." (PMID 21998152, 2011).
cancer (22 papers, 2011 to 2025). A tumor composed of atypical neoplastic, often pleomorphic cells that invade other tissues. "SSRP1 is often upregulated in multiple cancers and has a well characterized role in assisting RNA Pol II during transcription elongation." (PMID 39706891, 2025). "Like other cancers, overexpression of SSRP1 has been reported in CRC, and high gene expression correlates with faster disease recurrence." (PMID 40563399, 2025). "The level of miR-28-5p is often downregulated in CRC cells, and transfection with miRNA mimic sequences leads to a decrease in SSRP1 expression, resulting in reduced proliferation, migration, and invasiveness of cancer cells." (PMID 40563399, 2025). "Similar findings were obtained in HCT116, SW620, and MCF7 cancer cells selected among lines naturally expressing high levels of SSRP1." (PMID 39184446, 2024). "In agreement with the embryo results, we found reduced viability of immortalized and transformed cancer cells overexpressing SSRP1 after the treatment with NSC-95397." (PMID 39184446, 2024). "High levels of SSRP1 in tumors are consistent with the consensus that glycolysis is dominant in cancer cells (Warburg effect)." (PMID 38719542, 2024). "SSRP1 is highly expressed in cancer and potently enhances replication origin assembly as we have previously shown." (PMID 39184446, 2024). "There are also microRNAs that regulate SSRP1 and have been shown to promote cancer progression or malignancy." (PMID 37756103, 2023). "High expression of SSRP1, the subunit most commonly cancer-related and specifically the target of drugs, is associated with poor OS (p < 0.01) by Kaplan–Meier analysis." (PMID 37974213, 2023). "We also discovered that DPM is a FACT-dependent cancer with overexpression of both subunits structure-specific recognition protein 1 (SSRP1), a poor prognosis indicator, and suppressor of Ty 16 (SUPT16H)." (PMID 37974213, 2023). "Recently, some researchers have also proposed that inhibition of FACT subunits by SSRP1 silencing enhanced apoptosis of cancer cells upon cisplatin treatment." (PMID 36691066, 2023). "HMGB1 showed a positive association with CDK1 (R = 0.51), SSRP1 (R = 0.57), H2AFV (R = 0.53), and HMGB2 (R = 0.57) genes in several cancer types and these data were visualized as a heatmap." (PMID 36230798, 2022). "FACT complex components, especially SSRP1, play important roles in regulating the cell cycle, gene transcription and DNA repair in cancer cells." (PMID 36539830, 2022). "We also provide an innovative therapeutic approach by targeting SSRP1 using CBL0137 to exert a synergistic anti-cancer activity with PARPi in BRCA1/2 wild-type and HR-proficient HGSC cells by impairing DNA repair via targeting HR pathway." (PMID 36539830, 2022). "It was found from qRT-PCR that SSRP1 expression rose up in 40 GC tissues compared with that in para-carcinoma normal ones." (PMID 35291495, 2022). "We then confirmed its cancer-dependency and further revealed SSRP1 inhibition with CBL0137 as another effective epigenetic-targeted therapeutic strategy against MYCamp-G3-MB." (PMID 33268769, 2020). "Twenty genes were found mutated orwith copy number alterations in at least five percent of three cancer cohortsand six of them (PHOX2A, NFYC, EST2, EIF2S1, SSRP1 and PARP1) associated withimpacted patient survival." (PMID 32159609, 2020). "SSRP1 is considered more like a target since it's more amplified in cancers at mRNA and protein levels." (PMID 30581774, 2018). "In addition to the transcriptional downregulation of MYC, CBL0137 is known to exert anti-cancer activity by inhibiting the NF-kβ pathway and via trapping of SSRP1 into chromatin." (PMID 39706891, 2025).
cancer (continued). "Along with epigenetic modifiers that were previously implicated in cancer cell fitness, such as CHD1, CHD4, DNMT3B, ELP3, SUPT16H, SUV39H2; novel hits ASH2L, RBX1 and SSRP1 were discovered as essential genes for both U373 and T98G cells suggesting common regulatory role." (PMID 37974198, 2023). "Although Ssrp1 has been shown to stimulate proliferation through cell cycle regulation in a variety of human cancers, the role, mechanism, and clinical significance of Ssrp1 in RA remain unclear." (PMID 36511897, 2022). "In addition, SSRP1 inhibitor Curaxin CBL0137 has shown anticancer effects in many preclinical cancer models and is currently in phase I clinical trials targeting solid tumors and hematological malignancies in adults." (PMID 33688504, 2021). "In particular, SSRP1 is reported to be a prospective target for anti-cancer small molecules." (PMID 24870930, 2014). "Notably, SSRP1 is overexpressed in number of major cancer types, thus, our discovery could have far-reaching implications for broadening the scope of PARPi." (PMID 36539830, 2022).
infection (7 papers, 2016 to 2026). The state of being infected such as from the introduction of a foreign agent such as serum, vaccine, antigenic substance or organism. "Because ICP22 is an immediate early protein, we also used immunofluorescence to visualize the localization of SSRP1 early in infection." (PMID 28611249, 2017). "We determined that SSRP1 was not redistributed upon infection with viruses deficient for ICP22." (PMID 28611249, 2017). "Using infection time courses and IBs, we determined if hSpt16SUMO or SSRP1 levels differ between VSV-eGFP and VSVM51R-eGFP infections." (PMID 40060670, 2025). "For example, two stress response genes, SSRP1, PCBP4, (and 6 other validated examples of proximal polyadenylation site usage after the infection produced shorter transcripts." (PMID 27354008, 2016). "UponVACV infection, early viral gene expression triggers a SUMOylated form of hSpt16to translocate from the cytoplasm into the nucleus, where it forms specialized,antiviral FACT complexes with SSRP1." (PMID 41114588, 2025). "Neither depletion of SPT6 nor FACT (SSRP1) resulted in significant dOCR induction in ΔICP22 or mock infection." (PMID 37524699, 2023). "Additionally, SUPT16H and SSRP1, another FACT subunit, are both upregulated by EBV during initial infection." (PMID 34572593, 2021). "Additionally, SSRP1 is redistributed within the nucleus upon infection in KOS-infected cells compared to mock-infected cells, although Spt16 and SSRP1 protein levels are not altered by infection." (PMID 28611249, 2017).
SSRP1 also shares sentences with these, for which no sentence is quoted: Sepsis (4 papers); bladder cancer (2); inflammation (2); malignant melanomas (2); prostate carcinoma (2); angiosarcoma (1); autoimmune disorders (1); brain injury (1); Cachexia (1); diabetic retinopathy (1); hematological malignancies (1); Hyperglycemia (1); leukaemia (1); lymphoma (1); non-small cell lung carcinoma (1); stomach cancer (1); thyroid cancer (1); triple-negative breast carcinoma (1).